LEP (leptin)
Diseases named in the same sentence as LEP in open-access papers (continued):
Sharing a sentence is not in itself a finding about the gene and the disease.
Obesity (continued). "The genetic screening of 454 families from our cohort, with severe obesity, identified 132 probands (29%) and 13 family members with homozygous or compound heterozygous (likely) pathogenic variants in LEP, LEPR, or MC4R." (PMID 37659411, 2023). "It is increasingly evident that dysregulation in leptin and adiponectin balance is a key player in obesity-associated cancer development and progression." (PMID 37629396, 2023). "It is understood that obesity, and thus, high levels of circulating leptin, are associated with being in a state of leptin resistance that impairs sensitivity to the action of leptin on reducing food intake and increasing energy expenditure." (PMID 37599685, 2023). "Fat intake increases the risk of obesity by decreasing serotonin and increasing leptin, leptin resistance, adipose tissue, fat mass, body weight, and energy intake." (PMID 36835164, 2023). "While a complete loss of leptin causes impaired glucose homeostasis leading to obesity and a T2D phenotype, liver-specific leptin knockout in mice increases lipid accumulation in the liver but increases insulin sensitivity." (PMID 36769005, 2023). "In mice, the obese phenotype is generated either by feeding standard mice a very high fat diet (i.e., diet-induced obesity) or utilizing mice with genetic mutations that lead to obesity (e.g., leptin or its receptor)." (PMID 37947629, 2023). "In mice, it has been demonstrated that hypothalamic Nnat expression is downregulated during fasting and upregulated following leptin injection, and Nnat-deficient mice showed hyperphagia and susceptibility to obesity in old age." (PMID 37630847, 2023). "Women with PCOS often present glucose and energy homeostasis disruptions, along with obesity and metabolic syndrome, which arise associated with raised circulating levels of leptin and insulin." (PMID 37493841, 2023). "The dietary fat has been linked to increased obesity risk in humans and animals through body fat and weight gain, increased leptin sensitivity, promotion of intestinal microbial destruction, and accumulation of TG and cholesterol." (PMID 36835164, 2023). "It is worth mentioning that excessive activation of the central endocannabinoid system is associated with impaired leptin signaling, which contributes to the development of obesity." (PMID 37510734, 2023). "Here, we present a retrospective clinical history of 92 children suffering from severe obesity due to LEP and 32 cases with LEPR deficiency, all from a single geographical region of Punjab, Pakistan." (PMID 37659411, 2023). "As the gradual transition from lean to overweight to obesity occurred, which is associated with the accumulation of adiposity, the serum adiponectin level decreased in parallel with the increase in serum leptin levels." (PMID 36790383, 2023). "High leptin levels are directly linked to obesity and later to the development of metabolic disease consequences such as cardiovascular disease, insulin resistance, and type 2 diabetes." (PMID 36839226, 2023). "Leptin is a secreted protein consisting of 167 amino acids that has been identified as the causative factor in ob/ob mice that exhibit marked obesity." (PMID 36902744, 2023). "Obesity is a systemic disease that causes systemic inflammation, insulin resistance, and hormone dysregulation, including high leptin, low adiponectin, and high IGF-I." (PMID 37345115, 2023). "Monogenic obesity is a rare form of obesity due to pathogenic variants in genes implicated in the leptin–melanocortin signaling pathway and accounts for around 5% of severe early-onset obesity." (PMID 37329217, 2023). "Both surgical and dietary weight loss reverted obesity-driven elevation of leptin and resistin levels, while only dietary weight loss reverted elevation of plasminogen activator inhibitor 1 (PAI-1)." (PMID 37698918, 2023). "Leptin resistance and hyperleptinemia in obesity enhance inflammation and a wide range of pathogenic mechanisms." (PMID 37367676, 2023).
Obesity (continued). "Investigation of available literature suggests that estradiol, leptin, and adipokines secreted by visceral adipose tissue are the crucial players in obesity-associated hypogonadism in men." (PMID 37629396, 2023). "Variation of the fat mass and obesity-associated protein (FTO) is associated with obesity and low concentration of leptin." (PMID 37612540, 2023). "Slc7a5 deficiency caused sympathetic dysfunction and leptin insensitivity in LepR-expressing neurons before obesity onset." (PMID 36862514, 2023). "Increasing the amount of AT in obesity causes a chronic increase in leptin concentration, affecting the progression of chronic inflammation." (PMID 37371961, 2023). "Leptin levels are positively correlated with body-fat mass, and leptin resistance is a hallmark of obesity and metabolic disorders such as type two diabetes." (PMID 37238961, 2023). "Leptin contributes to the low-grade inflammatory state characteristic of obesity, which predisposes to the development of autoimmune diseases." (PMID 37686844, 2023). "Leptin levels were associated with IL-6 in a study investigating the relationship of these adipocytokines with overweight and obesity in participants at different ages." (PMID 37242271, 2023). "Monogenic types of obesity are caused by a mutation in one of genes LEP, LEPR, POMC, PCSK1, and MC4R, which encode proteins of the leptin–melanocortin system." (PMID 36983642, 2023). "Aside from the environment, obesity is associated with genes such as leptin and contributes to overweight conditions in cattle, pigs, and African elephants (Loxodonta africana)." (PMID 37048389, 2023). "The plasma level of leptin is increased by insulin resistance, and leptin positively influences the activity of the nervous system, which leads us to think of hypertension associated with obesity." (PMID 36677012, 2023). "Elevated leptin levels arising from leptin resistance in obesity are associated with insulin resistance and CVD." (PMID 37841878, 2023). "In a minority of patients, obesity is caused by gene defects affecting the hypothalamic leptin-melanocortin pathway resulting in early-onset obesity and hyperphagia (i.e. disturbed appetite signaling)." (PMID 36876127, 2023). "In human trials acupuncture emerges as a potentially effective complementary treatment of obesity as it is thought to induce loss of appetite, down-regulates insulin and leptin resistance, and lowers ghrelin as well as glucose levels." (PMID 37795371, 2023). "Genetic disruption of key molecular components of the hypothalamic leptin–melanocortin pathway causes severe obesity in mice and humans." (PMID 37661743, 2023). "The metabolic changes associated with obesity, particularly circulating levels of hormones such as leptin, insulin, and ghrelin, seem to negatively affect the olfactory function of individuals." (PMID 36837824, 2023). "Leptin is a hallmark of obesity and an important appetite suppressant that acts as a signal to the brain, passes through the blood–brain barrier (BBB), and affects the hypothalamus to deliver information about fat storage." (PMID 37372025, 2023). "Elevated levels of leptin and reduced adiponectin are common in obesity and have been associated with HCC development." (PMID 37834153, 2023). "In obesity, a low zinc diet alters leptin production, although in this case zinc deficiency leads to increased rather than decreased serum leptin levels." (PMID 38260166, 2023). "There is a great body of evidence that most common forms of obesity are associated with excessive circulating levels of leptin, secondary to leptin resistance." (PMID 37629396, 2023). "Analysis of the leptin–LepR binding interfaces reveals the molecular basis for human obesity-associated mutations." (PMID 37002197, 2023). "Leptin is an adipokine that regulates body metabolism and appetite, and obesity is associated with leptin dysregulation, which increases the risk of cardiovascular disease." (PMID 36839173, 2023).
Obesity (continued). "This agrees with the observation that leptin resistance in obesity (per BMI) is associated with worse bone outcomes." (PMID 37887382, 2023). "IN leptin was shown to reduce appetite and induce weight loss in rats with diet induced obesity (DIO) to the same extent as in lean rats." (PMID 37371113, 2023). "Sleep duration is also associated with metabolism (e.g. leptin level) and energy intake, which will lead to fat accumulation and obesity." (PMID 37173647, 2023). "In summary, obesity’s association with AD involves complex interactions such as leptin resistance, insulin dysfunction, altered glucose metabolism, oxidative stress, amyloid-beta disturbances, and brain atrophy." (PMID 38026693, 2023). "This review explores the complex relationships among age-associated obesity, the insulin–leptin axis, and the Cdc42 signaling pathway." (PMID 38068822, 2023). "Obese rodents e.g., the leptin-deficient (ob/ob) mouse exhibit remarkable behavioral changes and are therefore ideal models for evaluating mental disorders resulting from obesity." (PMID 37034162, 2023). "For example, in influenza infection, leptin resistance is a major infection susceptibility factor in individuals with obesity." (PMID 37217748, 2023). "Impaired leptin/adiponectin ratio was implicated in the pathogenesis of cardiac remodeling in obesity and metabolic dysfunction being a marker of inflammation." (PMID 37358728, 2023). "BAP31 mRNA and protein levels were reduced in WAT of diet-induced obese mice, and also decreased in leptin deficiency-induced obese mice, pointing the reasonable roles involved in obesity." (PMID 37063427, 2023). "Obesity has been described to be associated with a chronic state of low-grade inflammation characterised by high levels of inflammatory proteins like leptin, interleukin(IL)-6, IL-8 and tumor necrosis factor-alpha (TNF-α) among others." (PMID 37215211, 2023). "Although the role of leptin and the associated leptin receptor gene in human obesity is progressively unraveling, it remains enigmatic and requires further exploration." (PMID 37762850, 2023). "Endoplasmic reticulum (ER) stress implicated in leptin resistance in the diet-induced obesity, which can accelerate the development of atherosclerosis forms the background of this study." (PMID 38084147, 2023). "Current or novel medications against monogenic forms of obesity, though available in many developed countries, are unfortunately lacking in Pakistan—a country with the world’s highest recorded prevalence of LEP-signaling deficiency." (PMID 37659411, 2023). "Previous research on cardiovascular risk factors in Spain using the same cohort of prepubertal children described here found that leptin concentration influenced the association between obesity and features of insulin resistance." (PMID 37242271, 2023). "In a study on common variants in the leptin gene, researchers showed an association of the AA genotype of the rs7799039 variant with the development of obesity in the population of South India." (PMID 36983642, 2023). "High-fat diets rich in long-chain saturated fatty acids, mainly C16:0, contribute to hypothalamic inflammation, which has been shown to be causative of central leptin resistance, contributing to obesity development." (PMID 36926037, 2023). "Many genes are involved in the leptin-melanocortin pathway that has been associated with monogenic obesity through their influence on food intake and energy expenditure." (PMID 37025415, 2023). "In fact, the regulation of leptin levels is one of the key factors of the disease, given its implications in the development of obesity-associated comorbidities, such as non-alcoholic fatty liver disease (NAFLD)." (PMID 36833178, 2023). "The association between obesity and methylation of the LEP and ADIPOQ genes has been confirmed by several studies." (PMID 37375898, 2023).
Obesity (continued). "On the other hand, monogenic obesity which is inherited in a Mendelian pattern is typically rare and is characterized by early-onset, high severity, and a single gene mutation in the leptin-melanocortin pathway." (PMID 36875450, 2023). "In mouse models of partial leptin deficiency, it was shown that a reduced leptin level counteracted diet-induced obesity, adipose tissue inflammation and enhanced insulin sensitivity and glucose tolerance." (PMID 38136564, 2023). "Obesity has been also linked to dysregulation in the leptin signaling pathway, which is associated with central suppression of the upper airway neuromuscular control and development of hypoventilation." (PMID 36435894, 2023). "The altered levels of adipokines in obesity, particularly the decrease in adiponectin and increase in leptin, are implicated in the pathogenesis of infertility." (PMID 38264286, 2023). "Mutations in the leptin gene or its receptor can lead to leptin resistance, resulting in increased appetite and reduced energy expenditure, leading to obesity." (PMID 37600709, 2023). "Monogenic obesity in humans accounts for only a small proportion of obesity, and a few of human obesity can be explained by mutations in leptin or leptin receptors alone." (PMID 37007087, 2023). "On the other hand, visfatin and leptin have been associated with obesity; therefore, increased physical activity is also proposed as a factor in reducing obesity." (PMID 37238961, 2023). "Fat intake also increases the risk of obesity by altering several hormones, such as serotonin and leptin." (PMID 36835164, 2023). "High leptin levels and leptin resistance in obesity are associated with insulin resistance, type 2 diabetes, increased risk of CV diseases, low-grade inflammation, and thrombosis." (PMID 36901837, 2023). "In this review, potential molecular mediators of FMC associated with obesity are discussed, including leptin, adiponectin, serum amyloid A, estrogen, and prolactin." (PMID 37626804, 2023). "The susceptibility of C57BL/6J mice to diet-induced obesity is typically characterized by changes in plasma insulin and leptin levels and insulin sensitivity at 6 weeks of age." (PMID 37007087, 2023). "Genetic studies related to leptin circulation have identified a leptin-decreasing allele linked to higher fat mass, BMI, and obesity in adults." (PMID 36835164, 2023). "This is most likely due to the fact that states of hyperleptinemia in overweight and obesity are associated with leptin resistance resulting in reduced energy expenditure, hyperphagia, hyperinsulinemia, hyperlipidemia, IR or diabetes." (PMID 37239098, 2023). "Leptin, a polypeptide hormone of 167 amino acids with an N-terminal secretory-signal sequence of 21 amino acids encoded by the ob gene, was originally described as a protector against obesity, since ob/ob mice (leptin-deficient) were obese." (PMID 36674935, 2023). "This study aimed to investigate the association of obesity phenotypes with leptin (LEP) and adiponectin (ADP)." (PMID 37853077, 2023). "Obesity causes hypothalamic–pituitary–adrenal dysregulation and changes in the plasma levels of cortisol, leptin, adiponectin, resistin, and insulin, which are hormones involved in emotional and mood regulation." (PMID 37046297, 2023). "According to a systematic evaluation, higher levels of IGF-1, IGFBP-3 and leptin and lower levels of adiponectin among obesity-associated protein biomarkers are correlated with an increased breast cancer risk." (PMID 36755926, 2023). "Mice with central PTP1B-deficiency are lean, sensitive to leptin, and partially protected from diet-induced obesity." (PMID 36674935, 2023). "In line with the development of (functional) leptin resistance in End.LepR-KO mice, obesity was associated with elevated leptin levels." (PMID 37217565, 2023).
Obesity (continued). "For example, alterations in the fatty acid compositions of lipids in the endoplasmic reticulum (ER) have been shown to affect obesity-associated ER stress and to improve glucose metabolism in a leptin-deficient mouse model of obesity." (PMID 37523383, 2023). "Leptin was discovered when looking for the cause of obesity in genetically significantly overweight mice." (PMID 37630700, 2023). "This mutation caused early-onset obesity and metabolic alterations, and identification of leptin was essential for consolidating the adipose tissue as an endocrine tissue with effects even upon the brain." (PMID 35164764, 2022). "HFD-induced obesity caused high plasma leptin and abnormal testosterone levels and induced an aberrant intra-tubular organisation (ITO) which is associated with an altered spermatids/spermatocytes ratio (2:1 instead of 3:1)." (PMID 35017550, 2022). "Some studies have suggested a role for leptin in explaining the link between obesity and increased risk of breast cancer." (PMID 35087024, 2022). "Associations have also been reported between increased risk of NHL and polymorphisms in obesity‐related genes such as leptin (LEP) and leptin receptor, key regulators of energy balance and immune function." (PMID 35398917, 2022). "Multiple links between obesity and cancer risk have been identified, including increased levels of growth hormones, leptin, insulin, and adipokines, which can directly contribute to tumor transformation and progression." (PMID 35103755, 2022). "A diet rich in saturated fat had an unfavorable adiponectin concentration and a higher leptin concentration, thereby intimating the association between this type of diet and obesity." (PMID 36381753, 2022). "In agreement with the distinct effects of ERs in adipocytes, it has been demonstrated that the ERα/Erβ ratio is associated with obesity and leptin production, with higher BMI values in cases with a shift to the prevalence of Erβ." (PMID 35202251, 2022). "Previous studies found that n-3 FA treatment was able to attenuate metabolic disorders associated with obesity, by limiting HF-induced glucose intolerance and liver steatosis, and mice fed n-3 FA displayed lower circulating leptin." (PMID 35406010, 2022). "Obesity and enhanced bone metabolism are linked to adipokines like leptin, and obese rats with elevated leptin receptor genes experience spinal ligament ossification, according to research." (PMID 36036007, 2022). "Leptin is upregulated upon food intake and in patients with obesity and decreases during fasting or weight loss." (PMID 35909571, 2022). "From which, leptin promoter G2548A (rs7799039: guanine > adenine) polymorphism was reported to be associated with increased leptin level, obesity, breast cancer, insulin resistance, and T2DM in many populations." (PMID 36381191, 2022). "Alterations in LEP, as well as other genes, are linked to obesity and promote the development of CRC through various signaling pathways." (PMID 35563103, 2022). "Like galectin-1, leptin is closely associated with obesity and these proteins are also associated with each other." (PMID 36295832, 2022). "Longer duration of breastfeeding has been linked with epigenetic modification to obesity-related genes such as the leptin gene, consistent with the well-described association of breastfeeding duration with lower risk of obesity in later life." (PMID 35192186, 2022). "Fat cell volume, BMI, waist circumference, and triglycerides and leptin concentrations, all markers of obesity, are associated with plasma DPP4 concentrations." (PMID 35885620, 2022). "A leptin homozygous frameshift mutation, G133_VfsX14, was associated with severe obesity in Pakistani consanguineous families." (PMID 35563103, 2022). "The presence of AG/AA polymorphisms in the leptin is associated with a 290% (OR 3.9) higher chance of obesity, and for adiponectin genes, the chances are 740% (OR 8.4) higher." (PMID 35703718, 2022).